UCP2 (uncoupling protein 2)
Diseases named in the same sentence as UCP2 in open-access papers (continued):
Sharing a sentence is not in itself a finding about the gene and the disease.
gallbladder cancer (6 papers, 2020 to 2025). "Uncoupling protein 2 (UCP2) promotes proliferation and chemoresistance via NF-κB/β-catenin axis in gallbladder cancer." (PMID 36457017, 2022). "In uncoupling protein 2 (UCP2) knockdown gallbladder cancer cells, proliferation and glycolysis is suppressed and IKKβ and downstream signaling molecules NF-κB/FAK/β-catenin was also downregulated." (PMID 34217312, 2021). "In recent years, different reports have indicated that UCP2 is highly expressed in cancer cells, such as pancreatic and gallbladder cancer cells, where it participates in metabolism and ROS level regulation." (PMID 33669111, 2021). "This study showed that UCP2 knockdown enhanced mROS production in gemcitabine-exposed gallbladder cancer cells." (PMID 33187225, 2020). "Notably, in gallbladder cancer cells, the knocking down of UCP2 can improve the sensitivity of cancer cells to gemcitabine." (PMID 33669111, 2021). "Interestingly, there was a report that chemosensitivity for gemcitabine was increased when UCP2 was knocked down in gall bladder cancer cells." (PMID 33187225, 2020).
glaucoma (6 papers, 2019 to 2024). Increased pressure in the eyeball due to obstruction of the outflow of aqueous humor. "In astrocytes, overexpression of Stat3 or knockdown of IκKβ/p65, caspase-8, and mitochondrial uncoupling proteins (Ucp2) can reduce ganglion cell loss in glaucoma mouse models." (PMID 36466782, 2022). "For instance, overexpression of Stat3 or C3, knockdown of IκKβ/p65, caspase 8 and mitochondrial uncoupling proteins (Ucp2) in astrocytes may reduce ganglion cell loss in glaucoma patients in the future." (PMID 36466782, 2022). "It is likely that over time in glaucoma, Ucp2 levels may fall, and this may be correlated with RGC loss." (PMID 30906248, 2019). "The identification of UCP2 in glaucoma suggests that UCP2 is a promising therapeutic target for enhancing mitochondrial autophagy, potentially mitigating RGC loss under conditions of elevated IOP." (PMID 39500360, 2024). "UCP2 expression is altered during different stages of glaucoma and increases with elevated IOP, and overexpression of UCP2 in RGCs significantly reduces cell death in mice with high IOP." (PMID 37566048, 2023). "Ucp2 expression is in fact altered during different stages of glaucoma, and appears to increase with increasing IOP." (PMID 30906248, 2019). "Relative to the housekeeping gene Tbp, Ucp2 expression is elevated early in glaucoma, but decreases with increasing disease severity (p < 0.05)." (PMID 30906248, 2019). "While these data lend support to the association between mitochondrial Ψm and ROS as well as the control of ROS by Ucp2, the most important evidence for their effect on cell and tissue physiology normally and during glaucoma must be determined in vivo." (PMID 30906248, 2019). "To test whether UCP2 may be a useful target to reduce oxidative damage in glaucoma, we established a series of inducible transgenic mouse lines that would either overexpress or delete UCP2 selectively in retinal ganglion or glial cells." (PMID 35628482, 2022). "Using other glaucoma models, previously published studies have demonstrated a beneficial effect for RGC survival when increasing mitophagy in IOP related glaucoma models, either directly, e.g., by Parkin overexpression or indirectly, e.g., by deletion of mitochondrial Ucp2." (PMID 32164182, 2020). "Herein, we test the hypothesis that increased Ucp2 expression will improve RGC survival in a mouse model of glaucoma." (PMID 30906248, 2019). "If increased ganglion cell Ucp2 expression reflects a physiological response to increased ROS early in glaucoma, artificially increasing Ucp2 may increase the ability of that stress response to increase cell survival." (PMID 30906248, 2019). "Alternatively, PPAR-γ could theoretically promote multiple counteracting effects that render transcriptional stimulation of Ucp2 unimportant in glaucoma." (PMID 30906248, 2019). "To determine whether Ucp2 expression is positively or negatively related to the progression of glaucoma, we analyzed publically available data from a microarray that determined gene expression changes in the retina and optic nerve heads of 10.5 month old DBA/2J mice and DBA/2J; Gpnmb+ controls." (PMID 30906248, 2019). "Rosiglitazone is a PPAR-γ-dependent transcriptional activator of Ucp2, and increases retinal Ucp2 expression, but does not seem to promote Ucp2 mediated neuroprotection in the microbead model of glaucoma." (PMID 30906248, 2019). "Ucp2 knockout, which enhances glial mitophagy, may also enhance trans-cellular degradation of damaged RGC mitochondria or other components to protect against mitochondrial damage in glaucoma." (PMID 36466782, 2022). "We confirmed that retinal Ucp2 expression can increase 24 h following exposure to 10 mg/kg RSG, and hypothesized that due to transcriptional activation of Ucp2, dietary RSG confers the same resistance to damage in glaucoma as transgenic Ucp2 overexpression." (PMID 30906248, 2019).
glaucoma (continued). "We found that the PPAR-γ agonist rosiglitazone (RSG), a well-known transcriptional activator of Ucp2, does not alter RGC survival during glaucoma, implying an additional need to characterize clinically useful molecules which regulate Ucp2 at post-transcriptional levels." (PMID 30906248, 2019). "We show that increasing RGC but not glial Ucp2 expression in transgenic animals decreases glaucomatous RGC death, but also that the PPAR-γ agonist rosiglitazone (RSG), an endogenous transcriptional activator of Ucp2, does not significantly alter RGC loss during glaucoma." (PMID 30906248, 2019).
Glucose intolerance (6 papers, 2009 to 2024). Glucose intolerance (GI) can be defined as dysglycemia that comprises both prediabetes and diabetes. "Similarly, in a β-cell-specific UCP2 overexpression mouse model, increased levels of UCP2 are associated with glucose intolerance, inadequate insulin secretion, and pancreatic β-cell failure in mice." (PMID 39707176, 2024). "β-cell-specific UCP2-overexpressing transgenic mice (βUCP2Tg) exhibited glucose intolerance and a reduction in insulin secretion." (PMID 35800776, 2022). "The aim of this study was to test the hypothesis that glucose intolerance in NntKO mice is mediated wholly or partly by UCP2." (PMID 19539600, 2009). "Third, we find that glucose tolerance is similar in NntKO mice whether or not UCP2 is present, showing that the NntKO glucose intolerance phenotype, at least in our experiments, is not mediated by UCP2." (PMID 19539600, 2009).
ovarian carcinoma (6 papers, 2011 to 2022). A malignant neoplasm originating from the surface ovarian epithelium. "The elevated UCP2 mRNA expression was associated with improved OS of Stage 1–2 and 3 and Grade 3 ovarian cancer patients." (PMID 35090503, 2022). "Ovarian cancer patients with high mRNA levels of UCP2 and UCP3 were predicted to have improved OS and PFS (p < 0.05)." (PMID 35090503, 2022). "The survival analysis revealed that highly expressed UCP1, UCP2, UCP3 and UCP5 were associated with longer OS, PPS and PFS in patients with ovarian cancer." (PMID 35090503, 2022). "Indeed, in the ovarian cancer cell line, it has already been shown that increasing mitochondrial ROS by inhibition or knockdown of the ROS‐protective uncoupling protein UCP2 enhances cisplatin‐induced apoptosis." (PMID 35318813, 2022). "The results showed that ovarian cancer tissues have a higher expression level of UCP2 than normal tissues; meanwhile, the expression levels of UCP4 and UCP5 were lower in ovarian cancer tissues." (PMID 35090503, 2022). "UCP2 and UCP3 protein expression increased during ovarian cancer progression and after aggregation in comparison to the MOSE-E with a significant increase in UCP3 for the adherent MOSE-L and MOSE-LTICv spheroids (p<0.05)." (PMID 33520711, 2020). "We show that in contrast to the more differentiated ovarian cancer cells, the putative CD44+/MyD88+ ovarian cancer stem cells express lower levels of pyruvate dehydrogenase, Cox–I, Cox-II, and Cox–IV, and higher levels of UCP2." (PMID 25237928, 2014).
status epilepticus (6 papers, 2012 to 2023). Status epilepticus is defined as a continuous seizure lasting more than 30 min, or two or more seizures without full recovery of consciousness between any of them. "Our observation that rats that underwent UCP2 antisense treatment were more susceptible to status epilepticus might be an evidence of neuroprotection elicited by UCP2." (PMID 30159115, 2018). "To this end, we observed increased expression of UCP2 after pilocarpine administration in the silent phase, reaching a peak on the fifth day after status epilepticus onset." (PMID 30159115, 2018). "Our data demonstrated that UCP2 expression was augmented in the rat hippocampus 3 days after status epilepticus (SE), reaching a peak on the fifth day, then returning to basal levels." (PMID 30159115, 2018). "Compared to sham-control, there was an increase in UCP2 immunoreactivity in neurons from the hippocampal CA3 subfield on the right side 24 h after KA-induced status epilepticus." (PMID 22849356, 2012). "Based on real-time PCR and western blot analyses, we demonstrated a significant increase in UCP2 mRNA in the hippocampal CA3 subfield after KA-elicited status epilepticus, followed by augmented UCP2 protein levels." (PMID 22849356, 2012). "We evaluated the neuroprotective role of UCP2 against seizure-induced hippocampal neuronal cell death under experimental status epilepticus." (PMID 22849356, 2012). "The present study also provided novel results to suggest that upregulation of UCP2 in the hippocampus following experimental status epilepticus exerts its anti-apoptotic action by interacting with Bax mitochondrial translocation and downstream cytochrome c-dependent apoptotic cascades." (PMID 22849356, 2012). "Oxidized protein level, translocation of Bcl-2, Bax and cytochrome c between cytosol and mitochondria, and expression of peroxisome proliferator-activated receptors γ (PPARγ) and UCP2 were examined in the hippocampal CA3 subfield following KA-induced status epilepticus." (PMID 22849356, 2012). "Expression of PPARγ and UCP2 increased 12–48 h after KA-induced status epilepticus." (PMID 22849356, 2012). "It follows that as an antioxidant, UCP2 may be activated during experimental status epilepticus, leading to decreased ROS production, reduced mitochondrial dysfunction, impeded apoptotic pathway and retarded neuronal injury in the hippocampus." (PMID 22849356, 2012). "As UCP2 are most prevalent in the nervous system, and a majority of the neurodegenerative disorders engages free radical production, it is reasonable to propose that UCP2 induction will be involved in these neurological disorders, including status epilepticus." (PMID 22849356, 2012). "SIRT1 activation following status epilepticus in rats has been shown to enhance PGC1α, superoxide dismutase 2 (SOD2), and uncoupling protein 2 (UCP2)." (PMID 38203294, 2023). "We also verified the localization of UCP2 immunoreactivity in mitochondria by co-immunofluorescence staining with the mitochondrial membrane protein, COX IV of hippocampal CA3 neurons on the right side, 24 h after KA-induced status epilepticus compared with sham-control." (PMID 22849356, 2012).
trauma (6 papers, 2009 to 2018). "Previous study reported that ghrelin protects rats against traumatic brain injury through up-regulation of UCP2." (PMID 30026681, 2018).
acute kidney injury (5 papers, 2019 to 2023). Sudden and sustained deterioration of the kidney function characterized by decreased glomerular filtration rate, increased serum creatinine or oliguria. "In in vivo and in vitro models of ischemic acute kidney injury, there was evidence that UCP2 was upregulated and helped renal tubular cells to survive." (PMID 31275989, 2019). "This study investigated whether capsaicin protects against LPS-induced acute kidney injury through TRPV1/UCP2 axis." (PMID 37528882, 2023).
chronic kidney disease (5 papers, 2013 to 2024). Impairment of the renal function secondary to chronic kidney damage persisting for three or more months. "It has been reported that UCP2 I/D heterozygous decreased the risk of end-stage renal disease (ESRD)." (PMID 24398006, 2014). "Selected UCP2 gene variants (such as the -866G to A gene promoter transition) are significantly associated with chronic kidney disease (CKD) and they may be informative for prediction of genetic risk for CKD." (PMID 24264044, 2013).
colorectal cancer (5 papers, 2013 to 2023). A primary or metastatic malignant neoplasm that affects the colon or rectum. "Likewise, loss of UCP2 rendered colon cells more prone to malignant transformation through metabolic reprogramming and disruption of redox homeostasis, promoting worse outcomes in colorectal cancer." (PMID 36275699, 2022). "It was found that the biomarkers of efferocytosis (AXL, CD36, UCP2) and macrophage repair indicators SPMs (RvD1, RvE1, LipoxinA4) were significantly increased in animal models and postoperative colorectal cancer patients." (PMID 36691021, 2023). "In agreement with our work on colorectal cancer, they showed that the role of UCP2 in ROS handling is related to its substrate transport function rather than uncoupling activity." (PMID 36275699, 2022). "Previous findings have demonstrated miR-15a-5p accelerated progression of colorectal carcinoma by regulation of the mitochondrial uncoupling protein gene (UCP2) and the constitutive photomophogenesis nine gene (COP9)." (PMID 35360837, 2022).
depression (5 papers, 2017 to 2026). "In a chronic mild stress (CMS) model of depression characterized by anhedonia, UCP2-deficient mice showed exacerbated depressive behaviors, whereas UCP2 overexpression produced antidepressant effects by suppressing the ROS-thioredoxin-interacting protein (TXNIP)–NLRP3 pathway in astrocytes." (PMID 41441267, 2025). "As a key modulator of mitochondrial function and ROS production, UCP2 upregulation in immune cells likely signifies a state of chronic metabolic stress that fuels the low-grade neuroinflammation characteristic of depression." (PMID 41601681, 2026). "While UCP2 polymorphisms have not been reported in GWAS for major depressive disorders there are several reasons why it would still be worth following up on." (PMID 28771482, 2017). "By prioritizing UCP2, SOD1, HK2, NDUFS4, and NEU1, our findings highlight novel, immune-mediated pathways in depression and nominate promising targets for future diagnosis and therapeutic intervention." (PMID 41601681, 2026). "Knockout UCP2 could lead to the activation of the nod-like receptor protein 3 (NLRP3) inflammasome in hippocampal astrocytes and induce depression-like behaviors in mice." (PMID 40108901, 2025). "In summary, exercise regulates signaling pathways such as NF-κB, NLRP3, UCP2, and cGAS-STING, reduces the release of mtDNA and pro-inflammatory factors, inhibits the inflammatory response, and decreases ROS production, thereby improving mitochondrial function and alleviating depression." (PMID 40699781, 2025).
diabetic nephropathy (5 papers, 2012 to 2023). "Accumulating evidence indicates that UCP2 has a central role in the development of diabetic kidney disease, causing mitochondria dysfunction and associated increase in total kidney QO2 and development of kidney tissue hypoxia." (PMID 38188249, 2023). "Furthermore, the involvement of UCP2-mediated mitochondrial leak respiration in diabetic nephropathy has been demonstrated in UCP2 deficient (UCP2-/-) diabetic mice, in which the absence of UCP2 protected from diabetic-induced injury." (PMID 38188249, 2023). "Diabetic nephropathy-related OxS is also improved upon elevation of miR-214 via using uncoupling protein 2 (UCP2) so as to affect signaling via ROS/AKT/mTOR pathway." (PMID 32962281, 2020).
myocardial infarction (5 papers, 2009 to 2025). Gross necrosis of the myocardium, as a result of interruption of the blood supply to the area, as in coronary thrombosis. "UCP2 overexpression also reduces mtROS production, reduces atherosclerosis formation in animal models, improves coronary artery endothelium-dependent vasodilation, and is associated with reduce risk of myocardial infarction in humans." (PMID 31706320, 2019). "Diabetic patients in this post-myocardial infarction cohort with UCP2 -866 AA/GA genotype have poorer survival and higher myeloperoxidase levels than their GG counterparts." (PMID 19527523, 2009). "Myocardial infarction treatment may target the SIRT1/UCP-2 axis, suggesting the importance of this pathway in CVDs." (PMID 41567643, 2025). "Interestingly, a common polymorphism in the promoter of the UCP2 gene (− 866G>A) results in reduced UCP2 expression, increased systemic oxidative stress, and an increased risk of myocardial infarction in men with T2DM independent of other traditional risk facts." (PMID 31706320, 2019).
prostate carcinoma (5 papers, 2011 to 2025). A carcinoma that arises from epithelial cells of the prostate gland. "Given that our experiments indicated that UCP2 is a bona fide target of miR-214, we hypothesized that suppression of miR-214 expression might be an underlying feature of human prostate cancer." (PMID 27129291, 2016). "In prostate cancer tissue the levels of UCP-2 were significantly higher than that in the adjacent normal tissues." (PMID 39941741, 2025). "Accordingly, our studies described in this paper suggest that mitochondrial uncoupling protein UCP2 involved in uncoupling mitochondria plays an important role in breast, ovarian leukemia, bladder, esophagus, testicular, colorectal, kidney, pancreatic, lung and prostate cancers." (PMID 21935467, 2011).
renal fibrosis (5 papers, 2018 to 2022). A final common manifestation of a wide variety of chronic kidney diseases characterized by glomerulosclerosis and tubulointerstitial fibrosis. "UCP2-deficient mice displayed mitigated renal fibrosis in ischemia/reperfusion injury (I/R)-induced mouse model of TIF." (PMID 31932578, 2020). "Moreover, UCP2-deficient mice displayed mitigated renal fibrosis in I/R-induced mouse model of TIF." (PMID 31932578, 2020). "Dysregulation of miR-15a-5p and miR-30e-5p (i.e., microRNAs that target the mitochondrial UCP2 gene) is implicated in DKD, particularly in experimental studies which have demonstrated the link between these miRNAs, podocyte injury and renal fibrosis." (PMID 36010558, 2022). "We hypothesized that modulation of hypoxia and HIF-1α by UCP2 regulates renal fibrosis through promoting lipid and ECM accumulation." (PMID 31932578, 2020). "In addition, UCP2 ablation exacerbates the high salt diet-induced cardiovascular and renal fibrosis in the ROS-dependent manner." (PMID 30116205, 2018). "Taken together, our data suggested that circMTND5 might contribute to mitochondrial injury and further promote renal fibrosis by sponging MIR6812; further, MIR6812 regulate UCP2 and PGC-1α to participate renal fibrosis in lupus nephritis." (PMID 36267809, 2022).
Abdominal obesity (4 papers, 2009 to 2022). Excessive fat around the stomach and abdomen. "In conclusion, the study shows that high protein diets based on both pork protein and soybean protein alleviated abdominal obesity in mice effectively by regulating lipid metabolism, probably via the UCP2-AMPK-ACC signaling pathway." (PMID 35563950, 2022).
brain trauma (4 papers, 2012 to 2021). "After brain injury, the UCP-2 promotion could be a self-protective regulatory mechanism, for it could provide negative feedback for ROS production." (PMID 33613273, 2021).